SCARB1 (scavenger receptor class B member 1)
Diseases named in the same sentence as SCARB1 in open-access papers (continued):
Sharing a sentence is not in itself a finding about the gene and the disease.
hepatoma (30 papers, 2009 to 2023). "Studies with a longitudinal design, more following data and paired controls are required to explore the impact of disease stages (such as fibrosis, or cirrhosis, or hepatocellular carcinoma) on the association of SCARB1 genotype with HCV infection." (PMID 27561198, 2016). "Results of IHC staining showed that SCARB1 was highly expressed in cancer tissues compared to adjacent normal liver tissues and its expression was related to hepatocellular carcinoma differentiation status." (PMID 33912215, 2021). "The expressions of SCARB1 in hepatocellular carcinoma tissue in 46 patients were detected by immunohistochemistry, and the correlation between its expressions and disease free survival of patient was calculated." (PMID 33912215, 2021). "Neither CAPN5 nor CBLB affected surface expression of SCARB1, CD81, CLDN1 and OLCN on human hepatoma cells." (PMID 30024968, 2018).
prostate carcinoma (28 papers, 2010 to 2025). A carcinoma that arises from epithelial cells of the prostate gland. "We found that SCARB1 expression positively correlated with prostate cancer, nodal metastasis status, and Gleason score while MAPK3K1 and S100A10 levels inversely correlated." (PMID 35740605, 2022). "Interestingly, bioinformatic analysis based on the TGCA dataset showed that SCARB1 expression was significantly increased in prostate cancer samples compared to normal tissues while MAPK3K1 and S100A10 expression was significantly reduced." (PMID 35740605, 2022). "Studies have also found that SCARB1 can be a potential target for prostate cancer." (PMID 33912215, 2021). "In our study, for the first time, we have identified increased expression of SCARB1 and MAPK3K1 and decreased expression of S100A10 in PCAFs compared to PNAFs even if the role of these genes in prostate cancer progression and androgen resistance is well known." (PMID 35740605, 2022).
Hypercholesterolemia (25 papers, 2009 to 2024). An increased concentration of cholesterol in the blood. "Therefore, excess cholesterol may be the underlying cause of how hypercholesterolemia causes impaired fertility in Scarb1-deficient mice." (PMID 35433675, 2022). "Scarb1 knockout–induced hypercholesterolemia may increase cholesterol levels in follicular fluid, which inhibit ABCA1 activity and result in overloaded cholesterol in oocytes." (PMID 35433675, 2022). "In our study we analyzed the impact of SCARB1 SNP rs5888 with serum lipid profiles and association with CAD in a Lithuanian population characterised by high morbidity and mortality from CAD and a high prevalence of hypercholesterolemia." (PMID 23510561, 2013). "We analysed the impact of SCARB1 single nucleotide polymorphism (SNP) rs5888 with plasma lipid profile and association with coronary artery disease (CAD) in a Lithuanian population characterized by high morbidity and mortality from CAD and high prevalence of hypercholesterolemia." (PMID 23510561, 2013). "In addition, it is known that GALNT2, LPA, SCARB1, and APOC1 are genes responsible for a hereditary form of hypercholesterolemia." (PMID 35203469, 2022).
myocardial infarction (25 papers, 2009 to 2025). Gross necrosis of the myocardium, as a result of interruption of the blood supply to the area, as in coronary thrombosis. "Furthermore, SCARB1 was found to be linked to an increase in high-density lipoprotein-cholesterol and a heightened risk of myocardial infarction." (PMID 37628612, 2023).
Sepsis (17 papers, 2010 to 2025). Sepsis is defined as life-threatening organ dysfunction caused by a dysregulated host response to infection. "Here, we show that TLR2, TLR4, CD36, P2RX7, VIMP, and SCARB1 are also expressed in myocytes and muscle and that muscular expression of TLR2, TLR4, CD36, and VIMP increases during sepsis." (PMID 31441598, 2020).
diabetes (16 papers, 2013 to 2024). "This suggests that SCARB1 may be involved in diabetes-related complications by regulating lipid homeostasis." (PMID 38168477, 2024). "Scarb1, namely scavenger receptor class B type I, could mediate high-density lipoproteins (HDLs) to rescue diabetes-impaired angiogenesis." (PMID 36834610, 2023).
melanoma (16 papers, 2015 to 2026). A malignant, usually aggressive tumor composed of atypical, neoplastic melanocytes. "The loss of SCARB1 has been demonstrated to downregulate TF MITF related to the melanocytic state in human melanoma, suggesting that ligand–receptor interaction may affect the cell state of signal receivers." (PMID 35903095, 2022). "Expression of FAM174B, MAD1L1, SCARB1, MFSD12, SEMA6A, SLC45A2, and TBC1D16 was found to be upregulated and associated with worse OS in melanoma patients, while only MFSD12 and SLC45A2 were associated with worse DFS for melanoma patients." (PMID 30385854, 2019).
Obesity (16 papers, 2010 to 2025). Accumulation of substantial excess body fat. "RBFOX2 function is decreased in the liver in diet-induced obesity, causing a Scarb1 isoform switch and alteration of hepatocyte lipid homeostasis." (PMID 36536133, 2022). "The genotypes of ACAT-1 AC, LIPC GA and AA, and SCARB1 TT; LDL-R A-A- and LIPC GA; and SCARB1 TT were interacted with overweight/obesity to increase systolic, diastolic blood pressure (SBP, DBP) and pulse pressure (PP) levels; respectively." (PMID 23109900, 2012). "The interactions of ABCA-1 (SBP and PP), LDL-R (DBP), LIPC (SBP and DBP), and SCARB1 (PP) and overweight/obesity on blood pressure levels were also detected." (PMID 23109900, 2012). "The SNPs of ABCA-1 (SBP and PP), LDL-R (DBP), LIPC (SBP and DBP), and SCARB1 (PP) were shown interactions with overweight/obesity to influence blood pressure levels (p < 0.01–0.001)." (PMID 23109900, 2012). "The genotype of SCARB1 TT interacted with overweight/obesity to increase PP levels, whereas the genotypes of ACAT-1 AA and CC interacted with overweight/obesity to decrease PP levels." (PMID 23109900, 2012). "When the obesity causal genes were overlapped with the fasted and fed networks, 7 genes (ADA, BBS5, CBL, CCND3, FASN, FTO and SCARB1) overlapped with PER1's downstream genes in the fed network (Fisher's Exact Test p-value = 0.037)." (PMID 20168994, 2010). "SCARB1 TT genotype interacted with overweight/obesity to increase PP." (PMID 23109900, 2012). "The SNPs of ABCA-1 (LDL-C and ApoA1/ApoB); LIPC (TC, LDL-C, ApoA1 and ApoB); LIPG (ApoB); MTHFR (TC, TG and LDL-C); MYLIP (TC and TG); PCSK9 (TG, HDL-C, ApoB and ApoA1/ApoB); PPARD (TG and ApoA1/ApoB); and SCARB1 (TG, ApoA1 and ApoB) interacted with overweight/obesity to modulate serum lipid levels." (PMID 23039238, 2012). "Likewise, in a study on diet‐induced obesity mice, it was reported that cholesterol level was reduced due to luteolin by regulating cholesterol efflux regulators such as scavenger receptor class B member 1 (SR‐B1), ATP‐binding cassette (ABC) transporter G1, and liver X receptor α (LXRα)." (PMID 39830909, 2025). "In another study involving diet-induced obesity mice, luteolin was involved in the regulation of cholesterol efflux genes such as liver X receptor α (LXR-α), scavenger receptor class B member 1 (SRB1), and ATP-binding cassette transporter G1 (ABCG1)." (PMID 36422285, 2022). "In the present study, we showed that the genotypes of ACAT-1 AC, LIPC GA and AA, and SCARB1 TT interacted with overweight/obesity to increase SBP levels, whereas the genotype of ACAT-1 CC interacted with overweight/obesity to decrease SBP levels." (PMID 23109900, 2012). "Consistent with our hypothesis, HFr promoted significant AS changes in LWT mice and LΔRbfox2 mice failed to induce obesity-specific AS events at Pla2g6, Scarb1 and Numb." (PMID 36536133, 2022). "While SCARB1 is a complex therapeutic target, the effect of SSO8.3 in decreasing the amounts of some of these lipid species in hepatocytes indicates that strategies aimed to promote the SR-BII isoform could contribute to alleviating obesity-induced inflammation in vivo." (PMID 36536133, 2022).
dyslipidemia (15 papers, 2009 to 2025). "Multivariate logistic regression analysis was performed to identify the associations of the APOE, SCARB1, PPARα genotypes with the prevalence of dyslipidemias in the study population." (PMID 23919842, 2013). "The associations of the SCARB1 and PPARα genotypes with dyslipidemia were found only in men." (PMID 23919842, 2013). "Our aim was therefore to assess the distribution of the APOE, SCARB1, PPARα genotypes in the Lithuanian adult population and to determine the relationship of these genotypes with dyslipidemia." (PMID 23919842, 2013). "The objective of this study was to assess the distribution of the APOE, SCARB1, PPARα genotypes in the Lithuanian adult population and to determine the relationship of these genotypes with dyslipidemia." (PMID 23919842, 2013). "We did not observe any association between the SCARB1 genotype and dyslipidemia in women." (PMID 23919842, 2013). "For complex disorders, variants in genes with clear biological and clinical importance, such as LDLRAP1, SCARB1, and NPC1L1 have been identified, corresponding to approximately 25% - 30% of the genetic variance for various dyslipidemia traits." (PMID 38938445, 2024).
coronary artery atherosclerosis (11 papers, 2013 to 2025).
Infertility (9 papers, 2015 to 2023). "Abnormal oocyte meiosis and activation induced by excess cholesterol directly cause infertility of Scarb1-deficient mice." (PMID 35433675, 2022). "Lipid metabolism disorders including a high plasma cholesterol level and high nonesterified cholesterol level in the extraovarian environment account for the infertility phenotype of Scarb1-deficient (Scarb1−/−) mice." (PMID 35433675, 2022). "A novel cause of infertility emerged from studies of female mice deficient in the HDL receptor gene (Scarb1)." (PMID 36596339, 2022). "The analysis of infertile women revealed polymorphisms on SCARB1, consolidating the link between cholesterol, its receptor, and fertility." (PMID 30044452, 2018). "Likewise, the mice deficient for Srb1 encoding the scavenger receptor class B type 1 (SRB1/SCARB1), also known as HDL-receptor, are infertile, with lower cholesteryl ester levels in the ovary and with defects in embryogenesis and implantation." (PMID 30044452, 2018). "Notably, in this context of high HDL-FCBI, female Scarb1-/- mice are infertile." (PMID 36596339, 2022). "In Scarb1-/- versus WT mice, the less abundant ovarian stroma—the connective tissue that binds the ovarian structures, including the follicles, together—could contribute to infertility." (PMID 36596339, 2022).
malaria (9 papers, 2013 to 2024). Malaria is a serious and sometimes fatal disease caused by a parasite that commonly infects a certain type of mosquito which feeds on humans. "Scavenger receptor class B type 1 (Scarb1), another host gene implicated in malaria LS infection, was found to be upregulated only in MBA-differentiated E14 cells." (PMID 32442532, 2020). "Nonetheless, complete development of P. berghei EEFs in this model may be attributable to the expression of Scarb1, Met, Cd81, Hgfr, and Prkcz; host genes previously implicated in malaria LS infection." (PMID 32442532, 2020).
viral infection (9 papers, 2012 to 2025). "While not specific to viral infection, SCARB1 acts as a phosphatidylserine receptor on testicular Sertoli cells which induce phagocytosis of spermatogenic cells." (PMID 32993136, 2020).
clear cell renal cell carcinoma (8 papers, 2015 to 2024). "Intriguingly, a recent study suggested that in clear cell renal cell carcinoma, cholesterol import mediated by Scavenger Receptor B1 (SCARB1) is imperative for lipid raft homeostasis and the PI3K/Akt pathway activation." (PMID 37542052, 2023). "Previous studies have found that inhibiting SCARB1 (a HDL cholesterol receptor) could kill and stop proliferation of clear cell renal cell carcinoma (ccRCC) cells." (PMID 35804456, 2022).
lymphoma (8 papers, 2018 to 2024). A malignant (clonal) proliferation of B- lymphocytes or T- lymphocytes which involves the lymph nodes, bone marrow and/or extranodal sites. "In summary, targeting SCARB1 with HDL NPs in cholesterol uptake–addicted lymphoma cells abolishes GPX4, resulting in cancer cell death by a mechanism consistent with ferroptosis." (PMID 33208460, 2021). "Cell death as a result of HDL NP exposure varied among the patient samples depending upon the lymphoma subtype and relative level of SCARB1 expression." (PMID 33208460, 2021). "Here, we verified the requirement of SCARB1 as a target of HDL NPs in these lymphoma cells using an anti-SCARB1 blocking antibody (Ab) and fluorescently labeled HDL NPs." (PMID 33208460, 2021). "Thus, it is also possible that HDL NPs targeting SCARB1 modulate important downstream second-messenger signaling pathways in cholesterol uptake–dependent lymphomas and that this also contributes to ferroptosis." (PMID 33208460, 2021). "Accordingly, our group explored whether HDL NP therapy targeting SCARB1 induced lymphoma cell death through a mechanism involving GPX4 and ferroptosis." (PMID 33208460, 2021). "Our in vitro data suggest that SCARB1 is a useful biomarker to identify patients with lymphoma where this targeted approach might be successful." (PMID 33208460, 2021). "The cholesterol-poor HDL NP targets SCARB1 in cholesterol uptake–dependent lymphoma cells." (PMID 33208460, 2021). "In conclusion, we report that HDL NPs target SCARB1 in cholesterol uptake–dependent and GPX4-dependent lymphoma cells revealing an apparent reciprocal oncometabolic response favoring an increase in de novo cholesterol biosynthesis at the expense of GPX4 expression." (PMID 33208460, 2021). "Thus, targeting of SCARB1 by HDL NPs with reduction of cell cholesterol uptake and compensatory increase in de novo cholesterol biosynthesis is a potential translational model for treatment of cholesterol uptake–dependent lymphoma." (PMID 33208460, 2021). "DiI HDL NP treatment of Jurkat cells, a SCARB1-negative T cell leukemia/lymphoma cell line, did not result in increased fluorescent signal over baseline, confirming that the HDL NPs target SCARB1 in B cell lymphoma." (PMID 33208460, 2021).
nasopharyngeal carcinoma (8 papers, 2015 to 2023). A carcinoma arising from the nasopharyngeal epithelium. "However, the mechanism underlying the regulation of SCARB1 in nasopharyngeal carcinoma through non-coding RNAs remains unclear." (PMID 37009875, 2023). "Our findings indicated that the SCAT8/miR-125b-5p axis promoted the malignant progression of nasopharyngeal carcinoma by driving the expression of SCARB1." (PMID 37009875, 2023). "Through analysis, a regulatory network was discovered that involved SCAT8/miR-125b-5p axis and contributed to the malignant progression of nasopharyngeal carcinoma by inducing SCARB1 expression." (PMID 37628612, 2023). "Moreover, as a ceRNA of miR-125b-5p, SCAT8 can not only regulate the expression of SCARB1, but also regulate the malignant progression of nasopharyngeal carcinoma." (PMID 37009875, 2023).
gastric cancer (5 papers, 2016 to 2024). A primary or metastatic malignant neoplasm involving the stomach. "One study showed that H19 effectively recruited the m6A reader YTHDF1, which significantly promoted the translation of SCARB1 and facilitated angiogenesis, specifically in gastric cancer." (PMID 38965575, 2024). "Consequently, H19 plays a regulatory role in gastric cancer (GC) angiogenesis through the YTHDF1/SCARB1 axis, offering additional insights into the mechanism underlying HIF‐1α/H19/YTHDF1/SCARB1 regulation in GC angiogenesis." (PMID 39135292, 2024).
Insulin resistance (5 papers, 2011 to 2024). Increased resistance towards insulin, that is, diminished effectiveness of insulin in reducing blood glucose levels. "Insulin resistance in the intestine has been associated with increased apolipoproteins, chylomicrons, de novo lipogenesis, and increased fatty acid and cholesterol uptake via CD36 and SCARB1." (PMID 22073239, 2011).
Nephropathy (5 papers, 2014 to 2025). A nonspecific term referring to disease or damage of the kidneys. "Taken together, these two sets of results suggest that SCARB1 expression may be downregulated in those with kidney disease in APOL1 high-risk genotypes." (PMID 39448372, 2025). "In our study, the SCARB1 signal (cg14849578) was found to be hypermethylated in those with kidney disease including APOL1 nephropathy, and results from the BIOS-BBMRI dataset show that this methylation signal was negatively associated with SCARB1 gene expression." (PMID 39448372, 2025).
pancreatic cancer (5 papers, 2016 to 2025). "Interestingly, in silico Kaplan–Meier analyses with the UCSC Xena database neither revealed a correlation of patient overall survival with SCARB1 (SR-B1) nor with ABCA1 expression in the Genomic data commons (GDC) The Cancer Genome Atlas TCGA pancreatic-cancer cohort." (PMID 35577388, 2022).
Adrenal insufficiency (4 papers, 2023 to 2026). Insufficient production of steroid hormones (primarily cortisol) by the adrenal glands. "The findings could help to shed a light on the mechanism underlying adrenal insufficiency, providing new insight that could link ACTH resistance, SCARB1 impairment, and defective nucleocytoplasmic transport." (PMID 37331934, 2023).
amyloid (4 papers, 2016 to 2024). "SAA receptors, such as SELS (glucose homeostasis and ER stress), ABCA1, ABCA7, SCARB1 (cholesterol efflux), CD36, TLR2, TLR4, CST3 (inflammatory signaling), FPR2 (chemotaxis and immune cell activation), and AGER (amyloidosis), have been reported previously." (PMID 27799725, 2016).